ALB (albumin)
Diseases named in the same sentence as ALB in open-access papers (continued):
Sharing a sentence is not in itself a finding about the gene and the disease.
liver fibrosis (continued). "Furthermore, JWXYS has been shown to elevate serum albumin levels and prevent liver fibrosis." (PMID 31871483, 2019). "Interestingly, all of the serum liver fibrosis indexes that were considered in the present study included at least one of the variables independently associated with PH grade, such as AST value, PLT count and ALB." (PMID 28820885, 2017). "Importantly, BCAA could be more beneficial for patients with advanced liver fibrosis whose serum albumin levels are decreased due to reduced mTORC1 signaling in hepatocytes." (PMID 28212548, 2017). "Both significant and advanced hepatic fibrosis could be predicted by a novel panel of serum biomarkers (Egy-Score) composed of CA 19-9, age, alpha-2- macroglobulin, total bilirubin, albumin and platelet count (in a regression equation) with good sensitivity and specificity." (PMID 24046790, 2013). "Immunohistochemical (IHC) analysis of tissue sections showed decreased expression of ALB, AAT, and KRT18 within the liver fibrosis region of CCL4‐induced mice." (PMID 40619613, 2025). "Db-RDA and correlation analyses indicated strong associations between gut microbiota composition and key clinical indicators of liver fibrosis, including ALT, AST, and ALB." (PMID 41228535, 2025). "To find out the effect of the different mesenchymal stem cells on ameliorating liver fibrosis, we assessed the liver function tests, including ALT and AST activities assessment, and the levels of total bilirubin and albumin." (PMID 41168842, 2025). "A microbial dysbiosis index calculated from PSC-associated genera correlated negatively with alpha diversity and serum albumin, while a positive correlation was observed with markers of cholestatic disease (ALP, GGT) and liver fibrosis (APRI)." (PMID 41951277, 2025). "In conclusion, the results of this study showed that gender, ALB, GLB, PLT, AKP, GGT and PT were independent predictors for CHB-related advanced liver fibrosis." (PMID 39286781, 2024). "In ALB, TBIL, LN, SOD, GSH-Px, α-SMA and HYP among the included literatures, only 2 articles were about hepatic fibrosis mice models." (PMID 38781262, 2024). "In the hepatic fibrosis models, curcumin can reduce ALP and TBIL content, increase ALB and A/G levels, and improve liver metabolism and synthesis function." (PMID 38781262, 2024). "The effects of curcumin on hepatic fibrosis rats or mice models mainly include three aspects: The indicators related to liver cell structure and function mainly include ALT, AST, ALP, ALB, A/G, TBIL, bax protein, bcl-2 protein and index of liver." (PMID 38781262, 2024). "It indicates that ALB levels can be elevated and ALT, AST, and TBIL levels can be reduced by MSCs intervention referred to liver fibrosis." (PMID 39104627, 2024). "We found that AST, ALT, albumin, CPT score, and ALBI score improved after SVR24, as in previous reports, and that liver fibrosis markers, such as type 4 collagen 7S and M2BPGi, also improved." (PMID 36729172, 2023). "Short-term treatment with a hepatic-stellate-cell-selective drug carrier, mannose-6-phosphate-modified human serum albumin (losartan-M6PHSA), was also effective at reducing liver fibrosis." (PMID 37509613, 2023). "The regression analysis results suggest that the concentration of albumin and the activity of GGTP are likely to have a substantial influence on the future management of liver fibrosis in patients with diabesity." (PMID 38137829, 2023). "Specifically, the mitigation of liver fibrosis post-HCV eradication is expected to lead to improvements in liver function, such as enhanced albumin and FGF-21 production." (PMID 37999215, 2023). "In our study, patients with diabesity and liver fibrosis were characterized by lower mean corpuscular volume (MCV), lower platelet count, higher RDW-CV, higher aminotransferase activity, lower albumin levels, and a higher percentage of HbA1c." (PMID 38137829, 2023).
liver fibrosis (continued). "Patients with severe liver fibrosis had significantly higher AST, ALT, GGT, RDW, ALP, and FT-LSM; a significantly lower ALB, CHO, and PLT was seen in the high grade of liver fibrosis." (PMID 35776774, 2022). "In addition, serum ALB levels were significantly reduced in the model group (p < 0.05), whereas serum ALT, AST, TBIL, and γ-GGT levels, which were used to evaluate hepatocellular necrosis and cholestasis associated with hepatic fibrosis, were drastically increased compared to the control group." (PMID 36059967, 2022). "Among patients with advanced liver fibrosis, patients who have high Fuc-Hp levels at EOT, high BMI, and low albumin levels at EOT should be carefully monitored for HCC occurrence after HCV elimination." (PMID 36542633, 2022). "Our study showed the Patients with severe liver fibrosis had significantly higher AST, ALT, GGT, and ALP, and a significantly lower ALB, CHO, and PLT was also seen in the high grade of liver fibrosis." (PMID 35776774, 2022). "Liver fibrosis was evaluated based on the NAFLD fibrosis score (NFS), which is a composite score of age, hyperglycemia, BMI, platelet count, albumin, and the AST/ALT ratio." (PMID 35223941, 2022). "As the liver fibrosis stage increased, the median levels of ALP, GGT, DBil, globulin, total bile acid, and INR increased, while the median levels of cholinesterase, albumin, prealbumin, and platelet counts decreased (all P < 0.001)." (PMID 33526976, 2021). "Generally, the non-invasive indirect biomarkers of liver fibrosis that contain other enzyme components, i.e., cholesterol (FORNS), bilirubin and albumin (HUI), or platelets alone (AP index), changed only marginally." (PMID 34501398, 2021). "Antibodies against α-SMA, albumin, and SOD were used to determine the effects of the miR-150 secretome on liver fibrosis, hepatic synthesis function, and antioxidant activity, respectively." (PMID 32152450, 2020). "In CCl4-induced rats of liver fibrosis, the water extract of PMR improved serum albumin which was an indicator of chronic liver damage and reduced the pathological grade of liver fibrosis as well as the occurrence of ascites." (PMID 32382557, 2020). "The higher frequency of AE did not correlate with hemoglobin, transaminases, total bilirubin, albumin, platelet count, CD4 count, cure rates, or degree of liver fibrosis." (PMID 29921760, 2018). "In our study, serum albumin level was a prognostic factor for patients with NAFLD-HCC, indicating that hepatic fibrosis is the prognostic factor." (PMID 29992975, 2018). "Generally, the serum ALT, AST, TBil, and ALB are the main markers for evaluating liver function; furthermore, the serum HA, LN, PC-III, and IV-C are important markers for evaluating liver fibrosis." (PMID 26221168, 2015). "In 51 patients with advanced liver fibrosis and a FIB-4 index score above 3.25, the median age, as well as ALT and AST levels, were higher, and serum albumin level and platelet counts were lower, than those of 52 patients with mild-moderate fibrosis." (PMID 26334270, 2015). "Serum ALB and GGT concentrations and PLT count differ significantly between patients with F0-F1 and those with F2-F4 liver fibrosis." (PMID 26088852, 2015). "Patients in the MHH cohort had slightly more advanced liver fibrosis with a higher mean APRI-Score, higher AST-/ALT- ratios, lower mean albumin levels and lower platelet counts." (PMID 25072849, 2014). "Indeed, except for simulations concerning changes in plasma albumin concentrations, which were based on clinical observations, the tested physiological changes were based on default values because the true values are unknown in our population with liver fibrosis." (PMID 38504260, 2024). "Based on clinical laboratory analyses, which showed 20% lower plasma albumin concentrations for patients with stage F4 liver fibrosis than those with no fibrosis, a 20% decrease in the fraction of blood chlordecone binding to plasma albumin was applied." (PMID 38504260, 2024).
liver fibrosis (continued). "In fact, FIB-4 and AFP decreased and albumin and PT improved from baseline to EOT and SVR12; thus, achievement of SVR may have a strong impact on the development of HCC by improving liver fibrosis and inflammation." (PMID 37268672, 2023). "Subgroup analysis showed that MSC-EV therapy significantly increased ALB in liver fibrosis, IRI, and NAFLD but not in ALI (P = 0.21)." (PMID 36983624, 2023). "As expected, the serum liver fibrosis markers were positively correlated with ALT, AST, TBIL, PT, LS, APRI, FIB-4, and Child–Pugh (C-P) classification (P < 0.05) and negatively correlated with ALB and PLT (P < 0.05)." (PMID 36510159, 2022). "Finally, PWH with significant liver fibrosis had higher ALT, AST, total cholesterol, triglycerides, albumin, CAP, while having lower platelets." (PMID 35207770, 2022). "After intravenous injection of LPS in rats with liver fibrosis, serum levels of ALT, AST, and TBil were significantly increased, while the level of ALB decreased significantly, and a large amount of inflammatory cell infiltration was observed in the portal area." (PMID 34256837, 2021). "Liver fibrosis progression involves hepatic stellate cells (HSCs) that produce a secreted protein that is acidic and rich in cysteine (SPARC), a specific protein-binding protein that binds strongly to albumin." (PMID 33810483, 2021). "Four hours after LPS and D-GalN injection in rats with liver fibrosis, rat serum ALT, and AST levels reached 400 U/L, and the TBil level reached 60 μmol/L, with increased plasma levels of ammonia and decreased levels of ALB." (PMID 34256837, 2021). "Because the Korean NHIS database did not include information about platelet count or albumin level, other liver fibrosis prediction scores such as FIB-4, NAFLD fibrosis score or Hepamet fibrosis score were not assessed." (PMID 34583706, 2021). "Accordingly, we create a new A group that avoids being trapped into the albumin pockets (pocket-escaping) and thereby construct a NIR probe, BNLBN, which effectively prevents this backdoor problem with increased imaging accuracy for liver fibrosis in vivo." (PMID 32218438, 2020). "CNALT patients displayed a higher platelet count (PLT) (170 000 vs 146 000/μL, P < 0.0001) and albumin (4.1 vs 4.1 g/dL, P = 0.0006) but lower AST (25 vs 51 U/L, P < 0.0001), alpha fetoprotein (3.2 vs 5.4 ng/mL, P < 0.0001), and liver fibrosis marker scores (all P < 0.0001)." (PMID 32782941, 2020). "In patients with C-CH, however, the maximum blood glucose was correlated with TP (r = −0.4749, P < 0.005), ALB (r = −0.5147, P < 0.001), HbA1c (r = 0.6027, P < 0.001), and 1,5-AG (r = −0.7020, P < 0.005) but not with the hepatic fibrosis markers." (PMID 28860506, 2017). "BGS were also significantly negatively correlated with the TP and ALB concentrations, but not with hepatic fibrosis markers, unlike in patients with NAFLD." (PMID 28860506, 2017). "We observed that continuous RAS was associated with a lower platelet count, lower prothrombin time, higher albumin, and higher total bilirubin in DCV/ASV failures, suggesting that advanced hepatic fibrosis blunts the reversion of a substitution to the wild-type." (PMID 28467359, 2017). "There were a few double-labelled α-SMA and albumin as well as FSP-1 and albumin double-labelled cells distributed near the fibrous septa, suggesting that hepatocyte EMT may contribute to the population of MFBs in CCl4-induced liver fibrosis." (PMID 27562139, 2016). "The aim of this study was to investigate the relevance of an index obtained from three metabolic variables (glycated albumin: GA, glycated hemoglobin: HbA1c, and branched-chain amino acids to tyrosine ratio: BTR) to the degree of liver fibrosis in hepatitis C virus virus- (HCV-) positive patients." (PMID 25861264, 2015).
liver fibrosis (continued). "Based on 12 available clinical parameters (age, sex, HBeAg status, HBV DNA, platelet, albumin, bilirubin, ALT, AST, ALP, GGT and AFP), a model to predict significant liver fibrosis (Ishak fibrosis score ≥3) was derived using the five best parameters (age, ALP, AST, AFP and platelet)." (PMID 21853071, 2011). "Only a 95-year-old male patient with platelet count of 107 × 109/L, AST 16 U/L, and ALT 11 U/L (AST/ALT ratio = 1.45), and presenting low serum levels of GGT 12 U/L, ChE 4,621 U/L, and albumin 31 g/L, had a FIB-4 score of 4.3 indicative of severe liver fibrosis, although the APRI index was 0.60." (PMID 21190397, 2011). "Liver enzymes, noninvasive liver fibrosis scores and liver function tests showed additive effects across metHC, AUD and metAUD compared to HC, with the largest effects in metAUD for GGT, AST, ALT, CRP, albumin, direct bilirubin, FIB-4, LiverRisk and NFS (p < 0.001)." (PMID 41780539, 2026). "Patients with F4 liver fibrosis tended to be older with a mean age of 46.5 ± 6.96 years, with significantly higher values of BMI, bilirubin, AST, ALT, INR, FIB-4, and APRI scores (p < 0.001), while total protein, albumin, Hb, platelets and APP values were significantly lower (p < 0.001)." (PMID 40550831, 2025). "Because the Korean NHIS database does not include information regarding platelet count or albumin level, we could not assess other liver-fibrosis prediction scores." (PMID 36474232, 2022). "As albumin and other proteins are produced by the liver, changes in these parameters may indicate liver fibrosis, but they are not used alone, but together with other parameters in different tests and scores." (PMID 35276784, 2022). "Patients with liver fibrosis had a higher incidence of the involvement of abdominal arteries, higher D-dimer and estimated glomerular filtration rate level, as well as worse liver functional reserve (elevated alanine transaminase, AST, bilirubin, and INR and decreased albumin)." (PMID 34124186, 2021). "Patients with clinically active disease had decreased clinical measures of albumin (a decrease indicates reduced liver function) and increased non-alcoholic fatty liver disease (NAFLD) fibrosis scores (a non-invasive score that identifies liver fibrosis), suggesting altered liver function." (PMID 35050125, 2021). "We had previously shown that albumin and its derivative, R-III (a retinol-binding protein-albumin domain III fusion protein), inhibited HSC activation by sequestering retinoic acid (RA) and that R-III administration reduced carbon tetrachloride (CCl4)-induced liver fibrosis." (PMID 33542418, 2021). "We had previously demonstrated that albumin and its derivative R-III (a retinol-binding protein-albumin domain III fusion protein) inhibited the transdifferentiation/activation of hepatic stellate cells (HSCs) to myofibroblasts and that R-III administration reduced liver fibrosis." (PMID 33086608, 2020). "Furthermore, the gut microbiota communities significantly correlated with clinical parameters including WBC count, RBC count, PLT count, Hb, TP, ALB, ALB/GLO, and HDL levels, which may be closely related to liver fibrosis." (PMID 32265857, 2020). "Likewise, we noted a dampening of inflammation (a regular accompaniment of hepatic fibrosis) by antiplatelet drugs, reflected in diminished expression of TNF-α, and normalized levels of various markers (ALT, AST, albumin, and total bilirubin) signaling preservation of hepatic function." (PMID 33381477, 2020). "However, clinically, for noninvasive examinations, serum liver fibrosis markers, such as haluronic acid (HA), laminin (LN), fibrinogen, alanine aminotransferase (ALT), albumin (ALB), and total bilirubin, which are included in this study, are increasingly used to diagnose liver fibrosis." (PMID 31915451, 2019).
liver fibrosis (continued). "It was shown that a highly significant positive correlation involved TLR4 expression, the progression of liver fibrosis, age, RNA, transaminases, total bilirubin and prothrombin time, and a highly significant negative correlation with platelet count and serum albumin." (PMID 29379592, 2017). "The cut-off levels of ALB and hepatic fibrosis markers could not be established in patients with NAFLD, unlike in the analysis of patients with C-CH (data not shown)." (PMID 28860506, 2017). "Also albumin and prothrombin time did not contribute to the prediction of liver fibrosis in our children." (PMID 19409076, 2009). "Indeed, simulation of a decrease in the fraction of blood chlordecone binding to albumin (related to the observed lower plasma albumin concentration for patients with stage F4 liver fibrosis than those with no fibrosis) resulted in a decreased steady-state plasma chlordecone concentration." (PMID 38504260, 2024). "In the present study, double-labelling immunofluorescence showed that some albumin-positive cells in the mouse fibrotic liver sections were positively stained with α-SMA or FSP-1, suggesting that some hepatocytes undergo EMT and may contribute to MFBs in CCl4-induced hepatic fibrosis." (PMID 27562139, 2016). "Recently, we reported albumin platelet product (APP) and modified APP (mAPP) as novel indices of liver fibrosis staging and prognosis in patients without alcoholic liver diseases." (PMID 38200049, 2024). "This reduction in liver fibrosis did not affect the serum markers of liver damage (ALT and AST) or serum markers of hepatic function (albumin and total protein)." (PMID 37242695, 2023). "The subjects with NAFLD had significantly increased BMI, higher levels of HbA1c, fasting plasma glucose, ALT, albumin, TG, lower levels of HDL, and a higher proportion of significant liver fibrosis relative to subjects without NAFLD." (PMID 28759632, 2017). "For example, several clinical trials have shown no significant changes in the serum ALB concentration, MELD score, or serum aminotransferase level in patients with hepatic fibrosis who underwent autologous bone marrow MSCs transplantation at the 12-month follow-up." (PMID 39104627, 2024). "The results revealed that liver fibrosis progression has a positive correlation with age, TLR4 expression, viral load, ALT, AST, total bilirubin and PT, and negative correlation with platelet count and serum albumin." (PMID 29379592, 2017). "Also, there is a more recent liver fibrosis score, FIB-5, that incorporates albumin levels that could not be calculated for our patients because albumin levels were not evaluated." (PMID 37170243, 2023).